AURKA (aurora kinase A)
Diseases named in the same sentence as AURKA in open-access papers (continued):
Sharing a sentence is not in itself a finding about the gene and the disease.
neuroblastoma (continued). "The combination of MLN8237 with AURKA siRNA resulted in a more profound inhibitory effect on neuroblastoma cell growth in a mouse model." (PMID 31920463, 2020). "Taken together, these results provide evidence that IMR32 neuroblastoma cells undergo cellular senescence and growth inhibition due to AURKA inhibition." (PMID 31920463, 2020). "As an AURKA-targeting inhibitor, MLN8237 caused a pronounced decrease in phosphorylated AURKA (pThr288) at different time points in the neuroblastoma cell line IMR32." (PMID 31920463, 2020). "The LIN28B-RAN-AURKA-MYCN signaling cascade in the development of neuroblastoma provides a new insight into the molecular mechanism by which AURKA rs8173 reduced the risk of WT." (PMID 31636670, 2019). "ShRNA-mediated AURKA gene silencing assays have demonstrated that reducing AURKA expression would inhibit cell proliferation in neuroblastoma." (PMID 31636670, 2019). "Aurora kinase A and B (AURKA/B) phosphorylate and stabilize N-Myc protein, which sustains N-Myc function in promoting NE phenotypes in neuroblastoma." (PMID 32039001, 2019). "Fortunately, MYCN amplification is found to co-occur with AURKA (encoding Auror-A kinase) gene amplification in NEPC, in a similar way to that in neuroblastoma." (PMID 30657058, 2019). "In contrast, LIN28B has been shown to be overexpressed in high-risk neuroblastoma, leading to increased MYCN expression and stabilization by both inhibiting the miRNA let-7, and increasing RAN and AURKA expression." (PMID 30200332, 2018). "Knockdown of AURKA has been shown to decrease N-myc protein levels and neuroblastoma cell proliferation." (PMID 29678897, 2018). "Expression of AURKA and/or B have both been correlated with poor prognosis in neuroblastoma and are candidates for targeting with specific inhibitors." (PMID 30326621, 2018). "Recent studies using Boolean modeling have also identified Greatwall/MASTL as an important regulator of the Aurora kinase (AURKA) network in neuroblastoma." (PMID 30068336, 2018). "In neuroblastoma, AURKA protein product regulates N-myc protein levels and plays a critical role in tumorigenesis." (PMID 29678897, 2018). "Previous study demonstrated that LIN28B promotes AURKA expression via inhibition of let-7, further driving neuroblastoma oncogenesis." (PMID 29678897, 2018). "We specifically studied MYCN, MYBL2, BIRC5, BARD1 and AURKA, poor prognosis markers of neuroblastoma, and CCNA2 and CCNE1 genes, involved in general carcinogenesis." (PMID 28467792, 2017). "Oncogenic action of BARD1 in neuroblastoma has been demonstrated to be exerted by stabilizing AURKA involved in aggressive neuroblastomas." (PMID 28467792, 2017). "It has been shown that MYC upregulates expression of Aurora kinases A and B in neoplasms, and that Aurora kinase A is known to stabilize MYCN protein in neuroblastoma." (PMID 28333115, 2017). "Screening for enhancers of ABT-199 sensitivity in MYCN-amplified neuroblastomas, we demonstrate that the Aurora Kinase A inhibitor MLN8237 combines with ABT-199 to induce widespread apoptosis." (PMID 26859456, 2016). "In neuroblastoma, aurora kinase A expression is correlated with MYC amplification and protects the MYC protein from degradation." (PMID 25884680, 2015). "Selective sensitivity based on MYCN status was recently shown for the AURKA inhibitor MLN8237 in neuroblastoma which is due to the stabilizing effect of AURKA on MYCN." (PMID 26497213, 2015). "A recent study performed in vitro and in a mouse neuroblastoma model demonstrated that inhibition of AURKA with MLN8237 or MLN8054 actually triggers degradation of NMYC mediated by the Fbxw7 ubiquitin ligase." (PMID 25277175, 2014). "AURKA is necessary for the growth of MYCN amplified neuroblastoma providing an essential function in stabilization of NMYC protein." (PMID 25277175, 2014).
neuroblastoma (continued). "Concurrent amplification of NMYC and AURKA is strongly associated with NEPC, and is also a frequent feature of the neuroendocrine childhood tumor neuroblastoma." (PMID 25277175, 2014). "As a molecular mechanism, we demonstrate that PTPRD interacts with aurora kinase A (AURKA), an oncogenic protein that is over-expressed in multiple forms of cancer, including neuroblastoma." (PMID 22305495, 2012). "In neuroblastoma AURKA has been found to be expressed at high levels in MYCN amplified tumors and required for the growth of MYCN amplified cells." (PMID 23226679, 2012). "We further demonstrate that PTPRD has a tumor suppressor function in neuroblastoma through dephosphorylating and destabilizing AURKA, leading to a downstream decrease of MYCN protein." (PMID 22305495, 2012). "Intriguingly, one of the primary functions of AURKA is the activation of PLK1 by direct phosphorylation of Thr210, and high expression of PLK1 is also significantly associated with high-risk neuroblastoma and unfavourable patient outcome." (PMID 22305495, 2012). "In order to confirm an in vivo interaction between PTPRD and AURKA in neuroblastoma, protein extract isolated from Kelly cells transfected with either the V5-tagged PTPRD cDNA or empty vector was immunoprecipitated with a V5 epitope antibody." (PMID 22305495, 2012). "Preclinical evaluations of a second generation AURKA inhibitor MLN8237 in pediatric cancers including neuroblastoma have been promising." (PMID 23226679, 2012). "In this report we demonstrate a novel in vivo interaction between the tumor suppressor PTPRD and the oncogenic AURKA protein in neuroblastoma." (PMID 22305495, 2012). "Clinicopathologic characteristics of the patients with neuroblastoma and AURKA protein expression." (PMID 39585848, 2024). "The T58 degron of N-Myc is found at the binding interface of the complex formed by the Aurora kinase A (AurA) and N-Myc, thus the interaction of N-Myc with AurA inhibits its ubiquitinylation in neuroblastoma by blocking the interaction of N-Myc with the E3 ubiquitin ligase SCFFbxW717,18." (PMID 37884585, 2023). "Moreover, the combined application of BRD4 inhibitor I-BET151 and AURKA inhibitor alisertib significantly inhibited the neuroblastoma cells growth and dramatically prolonged the survival time of neuroblastoma xenograft mice." (PMID 36187481, 2022). "In particular, in neuroblastoma, a severe childhood cancer that arises from highly proliferative migratory cells of the neural crest, AURKA is highly expressed relative to normal tissues, and also displays a critical function by binding to and stabilizing the oncoprotein N-Myc." (PMID 34884931, 2021). "Together, these results suggest that PHA-680626 is a strong and effective CD inhibitor, preventing the AURKA/N-Myc interaction in cultured cells, triggering N-Myc degradation, and impairing the viability of neuroblastoma cell lines that are N-Myc-addicted for their proliferation." (PMID 34884931, 2021). "However, recent studies demonstrating the physical interaction between the mitotic kinase AURKA and N-Myc sequesters the latter from proteolytic degradation, paved the way for a novel, promising chemotherapeutic approach in neuroblastoma." (PMID 34884931, 2021). "Finally, the combination of MLN8237 treatment with AURKA small interfering RNA transfection were adopted to evaluate the inhibitory effect on neuroblastoma cells." (PMID 31920463, 2020). "Expression of AURKA among other genes was directly inhibited by miR-186 in neuroblastoma cells." (PMID 33245732, 2020). "However, as they were designed as ATP-competitive inhibitors of AURKA, they exhibited modest effects on N-Myc-amplified neuroblastoma cells." (PMID 33167327, 2020).
neuroblastoma (continued). "Because the stabilization of MYCN is a critical function of AURKA in human neuroblastoma, we want to validate whether the inhibition of AURKA induces MYCN degradation in our study." (PMID 31920463, 2020). "In summary, our study confirmed that none of the AURKA polymorphisms (rs1047972 C>T, rs2273535 T>A, and rs8173 G>C) were associated with neuroblastoma susceptibility in two distinct Chinese populations." (PMID 29678897, 2018). "In conclusion, our results indicate that none of the AURKA polymorphisms are associated with neuroblastoma susceptibility in two distinct Chinese populations." (PMID 29678897, 2018). "AURKA has also been shown to interact with MYCN in neuroblastoma and may play important roles also in other tumors." (PMID 28358317, 2017). "Aurora kinases expression and amplification, especially AURKA, are negative prognostic markers indicating high-risk disease in drug-resistant neuroblastoma cells." (PMID 27256407, 2016). "We hypothesized that by reducing aurora kinase A activity we may enhance the cytotoxic effect of cisplatin by overcoming the increased production of BDNF in surviving neuroblastoma cells, as a consequence of reduced aurora kinase-dependent BDNF translation." (PMID 27256407, 2016). "Here, we studied the effects of the pan-aurora kinase inhibitor tozasertib (VX680, MK-0457) and the aurora kinase inhibitor alisertib (MLN8237) that shows some specificity for aurora kinase A over aurora kinase B in a panel of neuroblastoma cell lines with acquired drug resistance." (PMID 25268132, 2014). "Here we tested tozasertib (VX680, MK-0457), a pan aurora kinase inhibitor, and alisertib, a second generation aurora kinase inhibitor that inhibits aurora kinase A and B with a higher affinity to aurora kinase A, in a panel of drug-resistant neuroblastoma cell lines." (PMID 25268132, 2014). "Testing of tozasertib, a pan aurora kinase inhibitor, and alisertib, a second generation aurora kinase inhibitor that inhibits aurora kinase A and B with a higher affinity to aurora kinase A, in a panel of drug-resistant neuroblastoma cell lines revealed differing activity profiles." (PMID 25268132, 2014). "Furthermore, consistent with the observation that AURKA is required for growth of MYCN amplified neuroblastoma, cells expressing high levels of MYCN were more sensitive to CCT137690 in comparison to cells expressing low or no MYCN." (PMID 23226679, 2012). "Several AURKA inhibitors are currently undergoing clinical evaluations for use as a single agent or in combination with existing chemotherapeutics in various phase I-II trials for different human cancers including neuroblastoma." (PMID 23226679, 2012). "Nevertheless, by analogy with neuroblastoma and other tumors, it can be assumed that some mitotic serine/threonine kinases (AURKA, AURKB) and transcription factors (SPT16) may be involved to maintain increased expression, particularly of the N-MYC oncogene in leukemia." (PMID 37606386, 2023). "However, N-Myc amplified neuroblastomas could be further sensitized to ABT-199 with the Aurora Kinase A inhibitor MLN8237, which results in a downregulation of Mcl-1." (PMID 30885150, 2019). "To date, no study has assessed the associations between AURKA SNPs and the risk of neuroblastoma." (PMID 29678897, 2018). "The recent development of AURKA inhibitors, along with impressive results in pre-clinical models of pediatric cancer, indicate that AURKA could be a therapeutic target of great value in the treatment of neuroblastoma." (PMID 22305495, 2012). "Pharmacodynamicstudies in a neuroblastoma xenograft mouse modelconfirmed that both SK4454 and SK5527 efficiently degraded AURKA invivo following a single intravenous dose of 15 mg/kg." (PMID 41252673, 2025). "Both SK4454 and SK5527 retained potentand selective AURKA degradation capacity, effectively reducing MYCNlevels in MYCN amplified neuroblastoma cells." (PMID 41252673, 2025).
neuroblastoma (continued). "In addition, previous studies demonstrate that the AURKA inhibitor alisertib could inhibit the growth of HCC and neuroblastoma in vivo via the AURKA-AKT axis, and PI3K/AKT activation directly influences HIF-1α-regulated glycolytic pathways and accelerates malignant progression." (PMID 41471272, 2025). "AURKA prevented the Fbxw7-mediated degradation of MYCN, which facilitated the growth of MYCN-amplified neuroblastoma cells." (PMID 38287009, 2024). "Aurora kinase A (AURKA) plays a role in mitosis and stabilization of the MYCN protein in neuroblastoma." (PMID 38313265, 2024). "Overexpression of LIN28B in neuroblastoma increases the levels of RAN by directly binding RAN mRNA, and then RAN induces phosphorylation of threonine 288 of AURKA and increases AURKA enzymatic activity, ultimately facilitating neuroblastoma progression." (PMID 39510185, 2024). "Aurora kinase A additionally protects from degradation MYCN, a major driver of oncogenesis in neuroblastoma." (PMID 37670947, 2023). "The expression of MYCN, AURKA, TGFBR1, and TGFBR2 is directly inhibited by miR-186, which can inhibit the tumorigenetic potential of neuroblastoma." (PMID 37426487, 2023). "Aurora kinase A (AURKA) is a serine/threonine kinase, whose mRNA expression is related to poor prognosis in neuroblastoma." (PMID 37072458, 2023). "Previous data showed that Aurora kinase A (AURKA) interacted with both MYCN and FBW7α, and counteracted FBW7α-mediated MYCN degradation in neuroblastoma cells." (PMID 35013218, 2022). "AURKA and PLK1 are up-regulated by MYCN and are frequently overexpressed in MYCN-amplified neuroblastomas." (PMID 33194665, 2020). "In neuroblastoma cells, LIN28B promotes AURKA expression and increases MYCN expression by repressing let-7 miRNAs." (PMID 33194665, 2020). "EV-miR-186 from NK cells induces cytotoxicity to MYCN-amplified neuroblastoma cells; targeted delivery of miR-186 suppresses tumor growth and improves the survival of a orthotopic mouse model of neuroblastoma by targeting MYCN, AURKA, TGFΒR1 and TGFΒR2." (PMID 32503543, 2020). "Subsequently, we demonstrated that LIN28B promotes the proliferation of neuroblastoma cells and defined RAN GTPase and Aurora kinase A (AURKA) as novel genes regulated by LIN28." (PMID 32923517, 2020). "In summary, as an AURKA inhibitor, MLN8237 can induce neuroblastoma cell senescence, G2/M cell cycle arrest, and cell growth in vitro and in vivo." (PMID 31920463, 2020). "AURKA and AURKB have been shown to regulate VEGF production and angiogenesis in endothelial cells directly and in neuroblastoma cells." (PMID 32039001, 2019). "Aurora kinase A inhibitors offer a promising new direction for treatment of neuroblastoma, particularly in MYCN-amplified neuroblastomas given the relationship between Aurora kinase A and N-MYC." (PMID 26771642, 2016). "CCT137690, an inhibitor of both Aurora kinase A and B, inhibited cell proliferation in MYCN-amplified neuroblastoma cells and tumor growth in MYCN-driven transgenic tumors in vivo." (PMID 26771642, 2016). "Inhibition of either the PI3K signaling pathway or the serine/threonine kinase AURKA was shown to decrease the stability of the MYCN protein and reduce the proliferation of neuroblastoma cell lines and xenografts." (PMID 26497213, 2015). "Collectively, our results suggest that OSU-03012 affects multiple cellular targets, including Aurora kinase A, to exhibit its growth suppressive and MYC and MYCN-destabilizing effects in neuroblastoma and other cancer cells." (PMID 25017515, 2014).
neuroblastoma (continued). "PTPRD has a tumor suppressor function in neuroblastoma through AURKA dephosphorylation and destabilization and a downstream destabilization of MYCN protein, representing a novel mechanism for the function of PTPRD in neuroblastoma." (PMID 22305495, 2012). "These subcategories included many genes known to be important in neuroblastoma pathogenesis, including ALK, AURKA and BDNF." (PMID 21731748, 2011). "Consequently, AURKA inhibitors indirectly destabilise MYCN and have shown potent antitumour activity in preclinical models of childhood neuroblastoma." (PMID 41561634, 2025). "The aurora kinase A inhibitors MLN8054 and MLN8327 unsettled the MYC-Aurora kinase A complex, leading to N-MYC destabilization and tumor deterioration in N-MYC amplified neuroblastoma." (PMID 39779613, 2025). "Taken together, these results suggested that a “MYCN” signature in subgroup 2 is potentially induced by AURKA overexpression in MYCN non-amplified neuroblastomas." (PMID 38553589, 2024). "Consequently, overexpression of AURKA counteracts the degradation of N-MYC, leading to the growth of neuroblastoma cells." (PMID 38553589, 2024). "In MNA neuroblastoma, the fatty acid metabolism process is promoted, and lipid metabolism becomes unbalanced due to the increased expression of ACADM and the inhibition of aurora kinase A (AURKA) and aurora kinase B (AURKB)." (PMID 39126035, 2024). "The main objective of this work was to quantify the expression of some genes (C-MYC, N-MYC, SPT16, AURKA, AURKB) that are more characteristic biomarkers for neuroblastoma with poor prognosis, but less studied in AML patients, including carriers of FLT3-ITD mutation with high allelic load." (PMID 37606386, 2023). "Then, we decided to additionally determine the expression of the N-MYC oncogene and the nearest circle of regulatory genes (SPT16, AURKA, AURKB) whose expression is often elevated in neuroblastoma and remains unstudied in adult patients with AML, including FLT3-ITD mutation carriers." (PMID 37606386, 2023). "The recent report of successful combined use of AURKA CD inhibitors and ATR inhibitors in MYCN amplified neuroblastoma strengthens the potential value of using compounds disrupting both AURKA activity and the interaction with N-Myc for the treatment of this highly aggressive tumor type." (PMID 34884931, 2021). "Of interest, a combined effect was observed by targeting GD2 ganglioside and AURKA in the inhibition of MYCN expression and induction of cell death in neuroblastoma cells Collectively, these data suggest that targeting ganglioside synthesis is a promising therapeutic strategy for liver cancer." (PMID 33803928, 2021). "This can occur either directly, since let-7 can target MYCN, or through activation of ras-related nuclear protein (RAN), which leads to increased transcription and phosphorylation of aurora kinase A (AURKA) and subsequent upregulation of MYCN, as shown in neuroblastoma." (PMID 32601913, 2020). "In vitro analysis demonstrated that the AURKA is required for the growth of MYCN-amplified neuroblastoma cell lines and the AURKA inhibitor alisertib (MLN8237) was able to inhibit the growth of neuroblastoma xenografts." (PMID 30200332, 2018). "The aurora kinase A inhibitor alisertib has demonstrated preclinical and/or clinical activity in several cancer types, including SCLC and other high grade neuroendocrine cancers such as neuroblastoma." (PMID 29088717, 2017). "Aurora kinase A stabilizes N-MYC, thereby increasing neuroblastoma cell proliferation." (PMID 26771642, 2016). "Notably, we also identified AURKA, a kinase critically required to stabilize the MYCN protein and whose inactivation triggers synthetic lethality in MYCN-amplified neuroblastomas." (PMID 25477524, 2015).